RN7SKP203 (RN7SK pseudogene 203)
Gene: Miscellaneous RNA gene on chromosome 2 (76,445,079 to 76,445,410, reverse strand). Ensembl gene ENSG00000200488.
Homologues: Paralogues in human: 7SK (79% identical), RN7SKP176 (77% identical), RN7SKP90 (77% identical), RN7SKP255 (76% identical), RN7SKP180 (76% identical), RN7SKP124 (75% identical), RN7SKP71 (75% identical), RN7SKP79 (74% identical), RN7SKP9 (73% identical), RN7SKP184 (73% identical), RN7SKP44 (73% identical), RN7SKP281 (73% identical), and 283 more.